MED12 (mediator complex subunit 12)
Diseases named in the same sentence as MED12 in open-access papers (continued):
Sharing a sentence is not in itself a finding about the gene and the disease.
leiomyoma (continued). "Leiomyosarcomas did not cluster together based on the presence of the established leiomyoma-associated driver mutations, unlike leiomyomas, which clustered according to the underlying MED12, HMGA2, or FH alteration." (PMID 41162745, 2025). "Therefore, we calculated the exclusive leiomyoma and normal myometrium peaks for H3K27ac, MED12, and CDK8." (PMID 40345582, 2025). "MED12 mutation-negative leiomyomas display copy number alterations in several other mediator complex subunits, such as MED18, MED8, CDK8, and the long non-coding RNA, RNA340 (CASC15)." (PMID 38279317, 2024). "Trials of these inhibitors should be carried out on patients with MED12-dependent leiomyoma." (PMID 37987267, 2023). "Here, we performed 3′RNA‐sequencing with 111 leiomyomas that had been previously classified as negative for a MED12 mutation, HMGA2 overexpression, and FH‐deficiency by Sanger sequencing or immunohistochemistry." (PMID 35822448, 2023). "Our data indicate that the presence of a MED12 mutation does not only affect the expression of genes in the leiomyoma but also in the myometrium which does not express the MED12 mutation." (PMID 36835153, 2023). "Here we showed that WNT2, WNT4, and WNT16 are overexpressed in leiomyomas, and that this upregulation was more pronounced in MED12-mutated leiomyomas compared to MED12 mutation-negative specimens, which is in line with previous reports." (PMID 36835153, 2023). "Here we confirmed that leiomyomas overexpress aromatase, but, more importantly, we showed that this increase is of greater magnitude in MED12-mutated tumors compared with non-mutated tumors." (PMID 36835153, 2023). "Our data indicate that in addition to marked overexpression of DCX in leiomyomas, in both mutated and non-mutated tumors with greater increase in the mutated leiomyomas, the myometrium of MED12-mutated specimens also overexpressed DCX." (PMID 36835153, 2023). "MED12 mutant fibroids had 4.4 times higher odds of shrinking in response to ulipristal acetate treatment as compared to HMGA2 driven fibroids (95% confidence interval 1.37–13.9; P = 0.013), and in a multivariate analysis molecular subclassification was an independent predictive factor." (PMID 36048862, 2023). "The MED12-mutant leiomyomas are smaller in size and more often subserous in location." (PMID 36835153, 2023). "In summary, we demonstrate that although there is a significant overlap in the differential expression of genes in MED12-mutated and non-mutated leiomyomas, the degree of change in expression is heightened for many genes in the MED12-mutated specimens." (PMID 36835153, 2023). "We initiated our investigation with high-throughput next-generation RNA sequencing (NGS) with RNA isolated from nineteen paired leiomyomas, including eight MED12-mutation-negative and eleven MED12-mutation-positive leiomyomas." (PMID 36835153, 2023). "MED12, the gene that codes for the mediator subunit 12 protein, is found on chromosome X. Alterations to MED12 have been found in the majority of women with fibroids in whom chromosomal changes have been noticed." (PMID 36703761, 2022). "Previous similar studies have shown that the silencing of MED12 could reduce the proliferation of leiomyoma cells via the wingless-type (WNT)/β-catenin signaling pathway." (PMID 35071776, 2022). "On the other hand, paracrine interactions between smooth muscle cells and tumor-associated fibroblasts are crucial for the progression of the MED12 mutant leiomyoma, as tumor-associated fibroblasts do not carry MED12 mutations." (PMID 35203298, 2022). "Wnt4, a β‐catenin activator, is highly expressed in MED12 mutant leiomyoma compared to nonmutant, and this mutation has been implicated with Wnt/β‐catenin pathway activation and stem cells self‐renewal, proliferation and fibrosis in ULs tissue." (PMID 35118811, 2022).
leiomyoma (continued). "Additionally, MED12 mutations have been implicated in the misregulation of WNT/CTNNB1 signaling, providing additional linage between two common mechanisms of leiomyoma development." (PMID 35203298, 2022). "We selected and further analyzed thirteen SE-lncRNAs and their corresponding protein coding genes which were differentially expressed in leiomyoma using quantitative real-time PCR (qRT-PCR) in different races and in leiomyomas with and without MED12 mutation." (PMID 35641855, 2022). "That study, together with the present results suggest that uterine fibroids without MED12 mutations are enriched in smooth muscle cells and contain a low amount of collagen fibers, and that MED12 mutations are associated with collagen-rich uterine fibroids." (PMID 35618793, 2022). "Next, we analyzed the expression of SE-lncRNAs and their associated mRNAs which were most significantly dysregulated based on fold change (leiomyoma vs. matched myometrium) in different racial groups and in tumors with and without the MED12 mutation." (PMID 35641855, 2022). "HMGA2 overexpression is the second major genetic alteration accounting for approximately 10% in uterine leiomyoma cases, but its expression is limited in the leiomyoma without underlying MED12 mutations." (PMID 35203298, 2022). "Expression level comparison between MED12 mutation positive and negative leiomyoma samples showed reduced expression level of hsa_circ_0060927 in MED12 wild‐type samples (2.04‐fold); however, the p value was not statistically significant (P = .775)." (PMID 31746073, 2020). "They found that, in contrast to uterine tumours, extrauterine smooth muscle tumours including leiomyomas, leiomyosarcomas, and angioleiomyomas do not have MED12 mutations." (PMID 30723247, 2019). "Further, overexpression of wild-type MED12 promotes proliferation of leiomyoma cells." (PMID 31089260, 2019). "Stem cells derived from leiomyoma tissue, but not myometrium, carry a mediator complex subunit 12 (MED 12) mutation in the majority of leiomyoma lesions." (PMID 30486855, 2018). "Interestingly, up to 80% (24/30) of the base changes we observed in Leiomyomas were specific to codon 44 (130 and 131 nucleotides) of MED12 coding transcript (ENS-100000374080)." (PMID 30619444, 2018). "In the present study, no mutations in exon 2 of MED12 were found in eight leiomyomas of deep soft tissue." (PMID 28591699, 2017). "None of the tumors displayed simultaneously more than one leiomyoma driver alteration, indicating that MED12 mutations, HMGA2 overexpression, and biallelic FH inactivation are mutually exclusive." (PMID 28592321, 2017). "This study confirmed the previously reported differences and discovered novel differentiating features for MED12-mutation-positive and -negative leiomyomas." (PMID 28432313, 2017). "The number of MED12-mutation-positive and -negative leiomyomas were negatively correlated [Spearman’s correlation coefficient −0.52, P value (P) = 1.6 × 10−18]." (PMID 28432313, 2017). "The known leiomyoma driver alterations were observed in 40% of the tumors: MED12 mutation frequency was slightly, but not significantly, lower in mitotically active ULs (36%, 9/25) compared to conventional leiomyomas." (PMID 28592321, 2017). "Apparently, “double negative” leiomyomas, i.e. those lacking clonal cytogenetic derivations as detected by classical cytogenetics as well as MED12 mutations represent a heterozygous group of tumors." (PMID 25506394, 2014). "This case encouraged us to investigate further leiomyomas remaining without MED12 mutations but with an apparently normal karyotype." (PMID 25506394, 2014). "Overall, the results suggest that leiomyomas with an apparently normal karyotype based on classical cytogenetics and lacking MED12 mutations represent a heterogeneous group of diseases." (PMID 25506394, 2014).
leiomyoma (continued). "It almost goes without saying that due to the high prevalence of fibroids MED12 mutations can be considered being the most frequent mutations in human tumors at all." (PMID 23738817, 2013). "MED12 was sequenced in an additional 143 leiomyomas and 73 normal myometrial tissues." (PMID 22428002, 2012). "All LMSP and leiomyoma-derived main population (LMMP) but none of the side or main population cells isolated from adjacent myometrium carried a mediator complex subunit 12 mutation, a genetic marker of neoplastic transformation." (PMID 22570742, 2012). "MED12 mutations were equally distributed among karyotypically normal and abnormal uterine leiomyomas and were identified in leiomyomas from both black and white American women." (PMID 22428002, 2012). "We therefore observed a total of 100/148 (67.6%) leiomyomas with MED12 variants, while no variants were detected in MED12 in the normal myometrial samples (p<0.0001)." (PMID 22428002, 2012). "Of specific note is that none of the 42 extrauterine leiomyoma samples analysed in this study harboured MED12 mutations." (PMID 23132392, 2012). "The observed MED12 mutations are probably not the driving force behind the malignant transformation, but rather indicate that these tumours have developed from leiomyoma precursors." (PMID 23132392, 2012). "Among our cases, only two leiomyomas exhibited 12q14∼15 rearrangements, and neither of these tumors harbored MED12 variants." (PMID 22428002, 2012). "Emerging evidence suggests that, in addition to hormonal influences, genetic mutations, particularly in the MED12 gene, may also contribute to the development of leiomyomas, although this has not been extensively studied in the adolescent population." (PMID 39944228, 2025). "Myometrial cells are the cell origin of leiomyoma, but the MED12 mutation status in non-neoplastic myometrial cells is unknown." (PMID 39273004, 2024). "In addition, the myometrial expression of WNT16 in MED12-mutated specimens was greater compared to myometrium of mutation-negative leiomyomas." (PMID 36835153, 2023). "The remaining 26 fibroids were found to be MED12 mutation-negative." (PMID 37113812, 2023). "Furthermore, several reports have indicated that the MED12 mutation rate in leiomyomas is about the same regardless of race/ethnicity." (PMID 37686244, 2023). "Finally, CASC15 expression was upregulated in many cancers and a potential hotspot for chromosome alterations in MED12-mutation-negative leiomyomas." (PMID 35641855, 2022). "In addition, we identified AKR1B10 expression in nine leiomyomas with no indication of FH-deficiency or alterations affecting MED12 or HMGA2." (PMID 36068196, 2022). "Additionally, DNA methylation and MED12 mutation together constitute a complex regulatory network that affects progesterone/PR-mediated RANKL gene expression, with an important role in activating stem cell proliferation and leiomyoma development." (PMID 34445194, 2021). "In addition, although the great majority of leiomyomas can be explained by defects in MED12, HMGA2, or FH, there is a small subset of leiomyomas where the driver alteration is unknown." (PMID 33352722, 2020). "Furthermore, overexpression of wild-type MED12 promotes proliferation of leiomyoma cells." (PMID 31089260, 2019). "It is conceivable that MED12-mutation-positive and -negative leiomyomas may respond differently to hormone-level changes, as well as to treatments, such as selective progesterone receptor modulators." (PMID 28432313, 2017). "Finally, we assessed the associations between the clinical factors and the number of MED12-mutation-negative leiomyomas with Poisson regression." (PMID 28432313, 2017). "As expected, histopathological leiomyoma variants tended to be MED12-mutation negative." (PMID 28432313, 2017). "Furthermore, all of the leiomyosarcoma samples (LMS-2, -5, -7 and -8) clustered in the SC2 sub-cluster of the leiomyoma group had no MED12 mutations." (PMID 27498619, 2016).
leiomyoma (continued). "All of the 4 leiomyoma specimens without MED12 mutations were included in the same cluster, SC2." (PMID 27498619, 2016). "Interestingly, the 4 leiomyoma specimens without MED12 mutations were included in the same sub-cluster, SC2." (PMID 27498619, 2016). "However, having identified those leiomyomas carrying MED12 mutations or/and cytogenetic abnormalities, there remains a small percentage of 10-15% of leiomyomas without these abnormalities." (PMID 25506394, 2014). "MED12 mutations are not exclusive to leiomyomas but seem to be specific to uterine malignancies." (PMID 22768200, 2012). "Our results demonstrated that the expression of several lncRNAs was affected by the presence of a MED12 mutation, which could be contributing to the differences in tumor size and progression in mutated leiomyomas as compared with non-mutated leiomyomas and merits further investigation." (PMID 38279317, 2024). "This aligns with recently published data in heterologous cell lines as well as leiomyoma tissue samples, which demonstrate that the presence of MED13 is a stabilizing protein in the submodule that compensates for any MED12 mutant-dependent interaction defect." (PMID 32094355, 2020). "We and others have previously shown that MED12, HMGA2, and FH aberrations result in distinct global gene expression patterns, suggesting that leiomyomas can be classified by gene expression profiling." (PMID 33352722, 2020). "The results demonstrated that all nine cases of IVL had a wild-type MED12 gene at codon 44, suggesting that IVL is a distinct smooth muscle tumour with a unique pathogenesis different from that of conventional leiomyomas." (PMID 30723247, 2019). "Furthermore, postmenopausal women without HT showed a trend towards fewer MED12-mutation-positive leiomyomas than premenopausal women; however, we observed a similar, yet weaker, trend also with mutation-negative tumours, but due to the limited sample size no conclusions can be drawn." (PMID 28432313, 2017). "Recently, it has been suggested that leiomyomas with bizarre nuclei can be divided into two subtypes based primarily on nuclear features; some tumors show significantly higher rates of HMGA2 immunoreactivity and frequent MED12 mutations and the others may occasionally be related to FH mutations." (PMID 28592321, 2017). "Understanding the growth mechanisms of MED12 WT and MUT leiomyomas may help guide individualized treatment options for patients." (PMID 41493967, 2026). "MED12 MUT leiomyomas have been reported to be highly responsive to ulipristal acetate treatment, and if CDK8 inhibitors prove effective for MED12 WT leiomyomas, they may facilitate precision medicine approaches." (PMID 41493967, 2026). "Both statistical tests yielded significant results, suggesting that MED12 enrichment in these genomic regions is not random and is higher than expected by chance in leiomyomas, whereas it is lower in normal myometrium." (PMID 40345582, 2025). "Hypo-methylated differentially methylated region that is adjacent to the PR binding site (PRBS) of the RANKL gene allows PR/MED12-G44D binding to the PRBS that promotes expression of RANKL and drives the stem cell proliferation and leiomyoma growth through the RANKL–RANK pathway." (PMID 40940746, 2025). "The results showed that leiomyoma tissues had significantly reduced LINCMD1 mRNA levels, regardless of patient race or MED12 mutation status, while miR-135b levels were elevated compared to matched myometrium samples." (PMID 39519092, 2024). "Inducing common mutations observed in fibroids in CRIP1+/PECAM1- myometrium cells, such as MED12 (exon 2, 131 G > A, G44D) or overexpression of HMGA2, could provide insight into fibroid etiology and models to evaluate alternative therapeutics." (PMID 37400623, 2023). "These tumors were also negative for MED12 and HMGA2 defects, as well as for mutations in genes encoding for proteins of the SRCAP complex, another recently discovered leiomyoma subtype." (PMID 36068196, 2022).
leiomyoma (continued). "This motivated us to explore the expression pattern of HMGA1 in our FFPE dataset, revealing significant upregulation of HMGA1 in leiomyomas of the FH subtype, but not in leiomyomas of the MED12 and HMGA2 subtypes." (PMID 33352722, 2020). "As expected, we detected significant upregulation of PLAG1 in leiomyomas of the HMGA2 and FH subtypes, but not in leiomyomas of the MED12 subtype." (PMID 33352722, 2020). "Together, these results establish that global loss of CDK8 chromatin binding is not an epigenetic feature of MED12 mutant leiomyomas." (PMID 32094355, 2020). "The correlation between tumor size (MED12 positive and negative) and different clinical characteristics of leiomyoma patients." (PMID 30619444, 2018). "For example, MED12 down-regulation was identified in the comparison of tumors and normal tissue, while the Mediator complex and subunits MED4 and MED19 were specifically identified in the IPA analysis of the older black/older white comparisons of leiomyoma." (PMID 23785396, 2013). "While further work remains to be done to clarify the reasons behind the observed differences, this study confirms a major role of MED12 in the tumorigenesis of leiomyomas, regardless of ethnicity." (PMID 22182697, 2011). "However, unlike conventional leiomyomas, mutations in MED12 are rarely observed in IVL, while MED12 mutations are the most common in conventional leiomyomas." (PMID 40276735, 2025). "Although alterations in MED12 and HMGA2 seem to be mutually exclusive, whether these genetic alterations induce the transformation of myometrial stem cells or maintain already existing leiomyoma stem-progenitor cells remains unclear." (PMID 34445194, 2021). "Thirty thousand six hundred and ninety-seven genomic sites co-bound by CDK8 and MED12 were identified in myometrium and leiomyoma tissue samples, with hierarchical clustering analysis revealing tissue-type-specific CDK8 submodule occupancy in myometrium and leiomyoma." (PMID 32094355, 2020). "Notably, genome-wide analyses of fibroids harboring different genetic alterations have revealed fibroid subtypes with distinct driver pathway genes, and MED12 and HMGA2 have been found to be the most common driver genes that together account for nearly 90% of all fibroids." (PMID 31089260, 2019). "This study confirms a major role of MED12 in the genesis of leiomyomas, regardless of ethnicity." (PMID 22182697, 2011). "All of the uterine leiomyosarcoma specimens that were clustered into the leiomyoma group were included in SC2, indicating that the DNA methylation profiles of the marker genes are similar to the marker gene profiles of uterine leiomyomas without MED12 mutations." (PMID 27498619, 2016). "Interestingly all classical leiomyomas exhibit MED12 protein expression while 40% of atypical leiomyomas, 50% of STUMP and 80% of leiomyosarcomas (among them the two mutated ones) do not express MED12." (PMID 22768200, 2012). "Aberrations in MED12, HMGA2, FH, and SRCAP complex genes account for most leiomyomas, but ~10% of leiomyomas do not harbor defects in any of these genes." (PMID 35822448, 2023).